TNF (tumor necrosis factor)
Diseases named in the same sentence as TNF in open-access papers (continued):
Sharing a sentence is not in itself a finding about the gene and the disease.
rheumatoid arthritis (continued). "For example, adalimumab, etanercept, and infliximab are agents that inhibit tumor necrosis factor-alpha (TNF-α), that is overexpressed in several autoimmune diseases, such as ankylosing spondylitis, psoriatic arthritis, ulcerative colitis, Crohn's disease, and rheumatoid arthritis." (PMID 23533306, 2013). "Irrespective of age, the TNF-α dysregulation could be associated to several diseases, such as diabetes type II, rheumatoid arthritis and atherosclerosis, among others." (PMID 23758797, 2013). "Anti-TNF-α agents are widely used to treat inflammatory disorders such as rheumatoid arthritis (RA)." (PMID 23882270, 2013). "Anti-tumor necrosis factor alpha (anti-TNF) biologic therapy is a widely used treatment for rheumatoid arthritis (RA)." (PMID 23555300, 2013). "Since TNF-α plays a pathological role in the development of rheumatoid arthritis (RA), patients with severe RA are treated with anti-TNF-α therapy." (PMID 23321200, 2013). "Biological therapies targeting tumor necrosis factor alpha (TNFα) have been introduced for the treatment of chronic inflammatory diseases including rheumatoid arthritis (RA) and Crohn's disease (CD)." (PMID 23809696, 2013). "Interestingly the cytokine profile in the skin of patients with chronic urticaria mimics that found in patients with psoriasis, psoriatic arthritis, and rheumatoid arthritis with increased expression of TNF-alpha and IL-10 and decreased expression of IL-2 and interferon gamma." (PMID 24167521, 2013). "The patient, in ASA physical status III, was affected by rheumatoid arthritis (RA) and treated with biologic immunomodulators and monoclonal anti-TNF antibodies." (PMID 23991339, 2013). "Therefore, TNF-α-targeting biological drugs are effective for treating rheumatoid arthritis." (PMID 23762085, 2013). "Although the complete absence of TTP (knockout mice) is associated with uncontrolled inflammatory responses and TTP influences cytokine levels in cell culture models, there are conflicting reports on whether TTP and TNF levels are correlated in rheumatoid arthritis patient samples." (PMID 24103357, 2013). "IL-1β and TNF-α are recognized contributors to the pathogenesis of joint diseases like rheumatoid arthritis (RA), thus leading to synovial fibroblast hyperplasia and the destruction of the extracellular matrix 8–10." (PMID 23331383, 2013). "In vitro apoptosis of peripheral monocytes in rheumatoid arthritis (RA) is disturbed and influenced by cytokine production and transmembrane TNF (tmTNF) reverse signaling." (PMID 24354986, 2013). "In the past 10 years, TNFα inhibitors have been demonstrated to be very effective in rheumatoid arthritis (RA), AS, and PsA." (PMID 23840241, 2013). "The impact of TNFα in the pathogenesis of autoimmune disorders such as systemic lupus erythematosus and rheumatoid arthritis (RA) has been widely accepted." (PMID 23079185, 2012). "TNF-α may play an important role in chronic inflammatory diseases such as rheumatoid arthritis." (PMID 23060289, 2012). "However, due to the multitude of human studies demonstrating that patients receiving TNF-α inhibitors for chronic inflammatory diseases (rheumatoid arthritis, Crohn disease) can develop reactivation TB disease, we acknowledge the significant risks of such treatment." (PMID 22761866, 2012). "This prediction is supported by the ablation of tonsilar GC structures in rheumatoid arthritis patients after TNF neutralization, an effective therapy in many RA patients." (PMID 23087687, 2012). "Tumor necrosis factor antagonists have been a major advancement in the treatment of several immune-mediated inflammatory diseases, including rheumatoid arthritis (RA), ankylosing spondylitis (AS), Crohn's disease, psoriatic arthritis, and psoriasis." (PMID 22666281, 2012). "In rheumatoid arthritis (RA), the pro-inflammatory cytokines tumor necrosis factor-α (TNF-α) and interleukin-1 (IL-1) are known to have pivotal roles in its pathophysiology." (PMID 23206933, 2012).
rheumatoid arthritis (continued). "The onset of Lupus Like Syndrome (LLS) has been described in patients with rheumatoid arthritis (RA) treated with anti-TNFα therapy but there is little literature on the occurrence of this entity in patients with SpA." (PMID 22336076, 2012). "The onset of LLS in patients with rheumatoid arthritis (RA) using anti-TNF therapy has been described, but there is little literature on the occurrence of this entity in patients with SpA." (PMID 22336076, 2012). "TNFα is a proinflammatory cytokine that plays a central role in the pathogenesis of rheumatoid arthritis (RA)." (PMID 22534470, 2012). "Also, the destructive effect of tumor necrosis factor α (TNFα) on joints in rheumatoid arthritis was found to involve DKK-1, and we have shown that platelet- and endothelial-derived DKK-1 could contribute to vascular inflammation in atherosclerosis." (PMID 23028464, 2012). "Abatacept has shown efficacy in a broad spectrum of rheumatoid arthritis (RA) patients from early stage to refractory diseases that are resistant to TNF blockers." (PMID 22997525, 2012). "B-cell depletion has become a common treatment strategy in anti-TNF-refractory rheumatoid arthritis (RA)." (PMID 22409963, 2012). "The treatment of rheumatoid arthritis (RA) patients with anti-tumor necrosis factor alpha (TNFα) biological drugs has dramatically improved the prognosis of these patients." (PMID 22838733, 2012). "Infliximab, a chimeric mAb targeting TNFα, is used to treat rheumatoid arthritis (RA), spondyloarthritis (SpA) and inflammatory bowel diseases." (PMID 21708018, 2011). "IL32 is a cytokine induced by TNF-α and may play a critical role in rheumatoid arthritis." (PMID 21423713, 2011). "Since the introduction of the anti-TNF antibody as a therapy for rheumatoid arthritis (RA) in the late 1990's the armamentarium of protein-based immune-modulating drugs has steadily increased." (PMID 22151889, 2011). "One of the key players in rheumatoid arthritis (RA) is TNF-α and therapies targeting this cytokine have already proved beneficial." (PMID 21611196, 2011). "For this purpose, non-steroidal anti-inflammatory compounds, corticosteroids, anti-TNF-α, and immunosuppressive drugs are widely used in the management of rheumatoid arthritis (RA) and lupus and other autoimmune diseases." (PMID 21261967, 2011). "Moreover, a sustained increased expression of IL-1β and TNF-α has been reported in several cases of chronic local inflammation, as in rheumatoid arthritis and inflammatory bowel diseases, where the anticytokine therapy is very effective, reducing symptoms and slowing or arresting tissue damage." (PMID 21772667, 2011). "In particular, TNF-α and IL-1 are prominent contributors to chronic inflammatory disorders including rheumatoid arthritis (RA)." (PMID 18955363, 2011). "Several studies in particular issued from randomised trials, indicated that the infection rate was up to two fold higher among rheumatoid arthritis (RA) patients receiving TNF inhibitors compared with those receiving methotrexate alone." (PMID 22046967, 2011). "Expenditure has increased rapidly for the treatment of rheumatoid arthritis (RA) due to the introduction of anti-tumor necrosis factor (TNF)-alpha and anti-interleukin (IL)-1 agents (infliximab, adalimumab, etanercept and anakinra)." (PMID 20478043, 2010). "The efficacy of TNFα blocker is now well established in patients with rheumatoid arthritis (RA), ankylosing spondylitis (AS) and psoriatic arthritis (PsA)." (PMID 20637100, 2010). "Data were used from 3 cohorts of patients with: early inflammatory arthritis (<10 weeks duration); established (>5 years duration) stable rheumatoid arthritis (RA); and RA being treated with anti-TNF therapy." (PMID 20149253, 2010). "Rituximab (RTX), which has been available for the treatment of lymphoma since 1998, was approved in 2006 for the treatment of rheumatoid arthritis (RA) patients who failed tumor necrosis factor (TNF)-alpha blockers." (PMID 20831776, 2010).
rheumatoid arthritis (continued). "This work studied the expression of the costimulatory molecule CD86 and the inhibitory receptor for IgG immune complexes FcγRIIb (CD32b), on B cells from rheumatoid arthritis (RA) patients, and the influence of anti-tumor necrosis factor (TNF) therapy." (PMID 20398308, 2010). "Tumor necrosis factor-alpha (TNFα) plays a pivotal role in rheumatoid arthritis (RA); however, the mechanism of action of TNFα antagonists in RA is poorly defined." (PMID 19660107, 2009). "Anti-TNF therapies have revolutionized the treatment of rheumatoid arthritis (RA), a common systemic autoimmune disease involving destruction of the synovial joints." (PMID 19460157, 2009). "Our results suggest that MEK/ERK and Egr1 are required for TNFα-regulated catabolic and anabolic genes of the cartilage extracellular matrix, and hence may represent potential targets for drug intervention in osteoarthritis or rheumatoid arthritis." (PMID 19144181, 2009). "In the RADIATE (Rheumatoid Arthritis Study in Anti-TNF Failures) trial, Emery and colleagues recently showed the improvement in 499 RA patients who had inadequate response to at least one anti-TNFα antagonist and who were treated with tocilizumab." (PMID 19886983, 2009). "Consider that patients with rheumatoid arthritis or Crohn's disease under TNF-blocking therapies can develop autoantibodies to nuclear antigens; therapeutic TNF blockades could thus lead to an exacerbation of certain autoimmune diseases such as SLE and to provoke lupus-like manifestations." (PMID 19121222, 2009). "Tumor necrosis factor (TNF) antagonists are used routinely in severe rheumatoid arthritis (RA) patients who failed conventional disease-modifying antirheumatic drug (DMARD) therapy." (PMID 19389237, 2009). "Three anti-tumor necrosis factor-alpha (anti-TNFα) therapies are approved for rheumatoid arthritis (RA) by the US Food and Drug Administration: infliximab (Remicade®), adalimumab (Humira®), and etanercept (Enbrel®)." (PMID 19886983, 2009). "TNF alpha blockade agents like infliximab are actually the treatment of choice for those rheumatoid arthritis (RA) patients who fail standard therapy." (PMID 19847310, 2009). "The increasing evidence supporting a central role of TNF-alpha in Alzheimer's suggested that, if appropriately administered, etanercept, already FDA-approved for certain inflammatory conditions mediated by TNF-alpha, such as rheumatoid arthritis, might be efficacious in Alzheimer's." (PMID 18644112, 2008). "The authors also found that HDACIs inhibited the expression of tumor necrosis factor-α, which functions to stimulate matrix degradation in rheumatoid arthritis, therefore suggesting a mechanism by which HDACIs may alleviate some effects of rheumatoid arthritis." (PMID 18959802, 2008). "Additionally, it remains to be clarified whether IL-10 decrease is a specific outcome of ESW treatment or mediated by TNF-alpha reduction since it has been shown that TNF-alpha up-regulates IL-10 expression in rheumatoid arthritis synovitis." (PMID 18237379, 2008). "Tumor necrosis factor-alpha (TNF-α) has been shown to be relevant for the physiopathology of rheumatoid arthritis (RA), and its inhibition by anti-TNF-α antibodies or recombinant soluble receptors results in a major improvement of this disease." (PMID 17408492, 2007). "When initiated early in rheumatoid arthritis (RA), significant control of joint inflammation and damage and improvement in physical function are obtained with disease modifying antirheumatic drugs (DMARDs), alone or in combination with tumor necrosis factor (TNF) antagonists." (PMID 16507128, 2006). "Bone marrow CD34+ cells from rheumatoid arthritis (RA) patients have abnormal capacities to respond to tumor necrosis factor (TNF)-α and to differentiate into fibroblast-like cells producing matrix metalloproteinase (MMP)-1." (PMID 16519794, 2006).
rheumatoid arthritis (continued). "The aim of the present work is to compare drug survival and safety of infliximab, etanercept, and adalimumab (tumor necrosis factor [TNF] antagonists) in spondylarthritis (SpA) with those of rheumatoid arthritis (RA)." (PMID 16620398, 2006). "Tumor necrosis factor alpha (TNFα) is a potent proinflammatory cytokine and is related to several inflammatory diseases such as rheumatoid arthritis (RA) and inflammatory bowel diseases (IBDs)." (PMID 17078892, 2006). "Stimulation of monocytes/macrophages after cell contact with preactivated T cells has been suggested to contribute to the excessive TNF-α production in rheumatoid arthritis (RA)." (PMID 16277671, 2005). "We report the case of a 63-year-old male patient with rheumatoid arthritis (RA) who experienced Epstein-Barr virus (EBV) reactivation during treatment with methotrexate (MTX) and anti-tumor necrosis factor-alpha (TNF-α) antibody, golimumab (GLM)." (PMID 41635385, 2026). "In rheumatoid arthritis (RA), TNF-α, interleukin (IL)-6, and other proinflammatory cytokines may play a key role in arrhythmogenesis through several mechanisms." (PMID 41517610, 2026). "RESULTS: Integrated analysis identified 34 common targets of Er Miao San (EMS) for rheumatoid arthritis (RA) treatment, with NFKBIA, RELA, and TNF recognized as the top hub genes." (PMID 41963877, 2026). "TNFα increases cAMP and activates the cAMP/PKA signaling pathway in synovial fibroblasts (SFs) from rheumatoid arthritis (RA) patients." (PMID 41601700, 2026). "Therefore, rheumatoid nodules, which are necrobiotic granulomas, may worsen with TNF‐α blockade." (PMID 41573269, 2026). "The moderate delay in modulating TNF-α suggests that PTD has a strong binding affinity and a sustained impact on this cytokine, which is critical in the pathogenesis of rheumatoid arthritis." (PMID 40332334, 2025). "Saffron was found to improve erythrocyte sedimentation rate (ESR), CRP, TNF-alpha, malondialdehyde (MDA), and total antioxidant capacity (TAC) levels in rheumatoid arthritis (RA) patients when administered 100 mg daily." (PMID 40365184, 2025). "TNF inhibitors (TNFis) have revolutionized the treatment of rheumatoid arthritis (RA)." (PMID 40428231, 2025). "Specifically, while anti-TNFα therapy is an effective treatment for Inflammatory Bowel Disease (IBD) and rheumatoid arthritis (RA), it paradoxically induces exacerbations in patients with MS30,31." (PMID 40475455, 2025). "Thus, adipose tissue can secrete and release cytokines such as TNFα and IL-6, which are common in inflammatory diseases like rheumatoid arthritis (RA), as well as cytokines known as adipokines (leptin, adiponectin, resistin, and visfatin, among others)." (PMID 40077690, 2025). "Infliximab, a TNF-α monoclonal antibody (mAb), is frequently used in the treatment of TNF-α-driven autoimmune diseases such as rheumatoid arthritis and inflammatory bowel disease." (PMID 41282287, 2025). "Among biologic monotherapy patients, 46.7% had rheumatoid arthritis, and 66.7% of BIA were TNF inhibitors." (PMID 40813910, 2025). "Collagen‐induced arthritis (CIA) rat models and tumor necrosis factor (TNF)‐α‐stimulated human rheumatoid arthritis fibroblast‐like synoviocyte (RA‐FLS) models were established to evaluate the therapeutic effects of DBD on RA." (PMID 40955790, 2025). "Previous literature supports our observations, demonstrating HERV-K element upregulation in response to TNF-α in various diseases, including cancers, HIV infection, rheumatoid arthritis, and schizophrenia." (PMID 40316021, 2025). "Some unsuccessful combinations for rheumatoid arthritis (RA), such as an IL1 inhibitor (IL1i) combined with a TNF inhibitor (TNFi), have negatively impacted this field in the past." (PMID 40529150, 2025). "Previous studies demonstrated that KYNA reduces TNF-α, S100A12, S100A8/9, and α-defensin production while increasing tumor necrosis factor-stimulated gene-6 protein (TSG-6) levels in rheumatoid arthritis." (PMID 41465233, 2025).
rheumatoid arthritis (continued). "PR3 can also cleave TNF-α, a key cytokine in inflammation, as evidenced by the successful use of anti-TNF-α treatments for Crohn’s disease, rheumatoid arthritis, and psoriasis." (PMID 40681487, 2025). "A study on rheumatoid arthritis showed that high-dose silibinin significantly reduced inflammatory markers (ESR, IL-8, IL-6, TNF-α, anti-CCP) and increased Hb, IL-10, and IL-2, compared to placebo." (PMID 39850538, 2025). "Rheumatoid arthritis (RA) is an autoimmune disease of unknown etiology, and one of the major causes of its development is a decrease in the ability of Treg to block the production of interferon γ (IFN ⁃ γ) and tumor necrosis factor α (TNF ⁃ α) by CD4 + CD25 + T cells." (PMID 40103816, 2025). "In rheumatoid arthritis (RA), chronic cytokine-driven inflammation (TNF-α, IL-6) promotes rheumatoid cachexia, accelerating muscle protein breakdown, reducing synthesis, and predisposing to low muscle mass, thereby linking inflammatory activity to creatinine declines via loss of muscle substrate." (PMID 41346979, 2025). "TNF-α Inhibitors: TNF-α inhibitors such as infliximab and etanercept, once used for autoimmune illnesses like rheumatoid arthritis, are now utilized to treat CNS disorders." (PMID 39861166, 2025). "In rheumatoid arthritis, co-treatment with anti-TNFα and anti-IL1 mAbs and the combination of anti-TNFα mAb and abatacept (CTLA4-Fc/T-cell activation inhibitor) have been evaluated." (PMID 41409758, 2025). "TGF-β1 induced cytokines, such as TNF–α, IL-1β, IL-1 MIP-1α and MMP-1, in cultured fibroblast-like synoviocytes from rheumatoid arthritis (RA) and osteoarthritis (OA) patients." (PMID 40141345, 2025). "Activated macrophages produce inflammatory cytokines, including tumor necrosis factor (TNF-α), interleukin (IL)-6, and nitric oxide (NO) that contribute to various autoimmune diseases such as inflammatory bowel disease and rheumatoid arthritis." (PMID 40076780, 2025). "One clinical study reported that urinary TNFα correlated with blood pressure in patients with HTN and psoriasis or rheumatoid arthritis." (PMID 40329016, 2025). "Infliximab, a chimeric monoclonal antibody targeting tumor necrosis factor-alpha (TNF-α), is widely used in the treatment of autoimmune diseases such as rheumatoid arthritis, Crohn’s disease (CD), and UC." (PMID 40144881, 2025). "IL‐17 plays a key role in the progression of rheumatoid arthritis in the TMJ, amplifying inflammation by stimulating the release of other pro‐inflammatory cytokines (such as TNF‐α, IL‐6, and IL‐1β), chemokines, and matrix metalloproteinases." (PMID 41006957, 2025). "2-DG also blocked signals induced by TNF-α, IL-1β, and interferon (IFN)-γ, efficiently alleviating a mouse model of inflammatory bowel disease and human rheumatoid arthritis." (PMID 38542934, 2024). "Kang and colleagues investigated the role of 3′SL in inflammation connected to rheumatoid arthritis and observed that cotreatment with IL-1β and 3′SL in THP-1 cells also reduced IL-1β, IL-6, and TNF mRNA and protein expression." (PMID 39325548, 2024). "Infliximab and adalimumab, the first FDA-approved anti-TNF-α agents, have been used in various rheumatic and dermatologic disorders, such as rheumatoid arthritis (RA), psoriasis, psoriatic arthritis (PsA), and ankylosing spondylitis (AS), for over two decades with proven efficacy and safety." (PMID 38842591, 2024). "Plasma levels of TNF-α are elevated in rheumatoid arthritis (RA), Henoch-Schonlein purpura (HSP), immunoglobulin A vasculitis (IgAV), chronic obstructive pulmonary disease (COPD), psoriasis (PS), and ankylosing spondylitis (AS) and are associated with the severity of disease." (PMID 38984140, 2024). "IL-32 induces the production of pro-inflammatory cytokines such as tumor necrosis factor (TNF)-α, IL-1β, IL-6, and IL-8, and IL-32 expression is highly increased in rheumatoid arthritis (RA) patients." (PMID 38675491, 2024).